STAT3 (signal transducer and activator of transcription 3)
Diseases named in the same sentence as STAT3 in open-access papers (continued):
Sharing a sentence is not in itself a finding about the gene and the disease.
diabetes (continued). "A series of logistic regression models were computed to determine whether SI was associated with the level of STAT3 phosphorylation in PBMCs, when adjusted to the potentially confounding variables sex, age, diabetes mellitus and hypertension." (PMID 40115872, 2025). "Moreover, STAT3 has been implicated in mediating β-cell epithelial–mesenchymal transition in the context of chronic pancreatitis-related diabetes, where its activation promotes β-cell dedifferentiation and loss, further contributing to diabetes progression." (PMID 40895573, 2025). "Thus, we conclude that ginsenoside Rg1 inhibits the STAT3 expression by miR-15b-5p to attenuate lung injury in mice with type 2 diabetes mellitus-associated pulmonary tuberculosis." (PMID 36248428, 2022). "The aim of the present study was to explore the relationship between single nucleotide polymorphism rs9891119 of STAT3 gene and type 2 diabetes mellitus (T2DM), which provides a basis for molecular genetic research on the pathogenesis of T2DM in Chinese Han population." (PMID 33833859, 2021). "Interestingly, data has also linked STAT3 to both normal and altered insulin signaling in the setting of diabetes." (PMID 27101310, 2016). "NAC and sevo-postC confer synergy in reducing myocardial IRI in diabetes and the possible mechanism may be associated with the increased expression of p-STAT3, APN restoration, and the decreased expression of Fox1 and CD36 in diabetic rats." (PMID 26783539, 2016). "Thus, in addition to causing dysregulation of immune‐related cells, STAT3 GOF variants may be implicated in diabetes by altering the development and function of pancreatic β‐cells." (PMID 38404237, 2024). "Besides, activation of STAT3 not only contributes to involvement in the development of diabetic insulin resistance in DM but also participates in the progress of diabetes-associated cardiovascular disease, such as myocardial interstitial fibrosis and myocardial infarction." (PMID 36532549, 2022). "Therefore, the suppression of STAT3 mediated by activated immune response could be closely associated with depression susceptibility to comorbid diabetes." (PMID 32655424, 2020). "Dysregulation of JAK/STAT3 can lead to cancer, inflammation, diabetes, and neurodegenerative disorders." (PMID 41596531, 2026). "Colivelin TFA is a neuroprotective peptide that can cross the blood–brain barrier and, therefore, interact with leptin-STAT3 signaling in the central nervous system to promote diabetes and DCM." (PMID 41170186, 2025). "Among them, hsa-miR-1248, hsa-miR-23b-5p, STAT3, Quercetin, Tretinoin, Particulate Matter, Simvastatin, Asthma, Hepatitis B, Hepatitis C, Diabetes Mellitus, and Pulmonary Fibrosis have an interaction relationship centred on CCL5." (PMID 40461634, 2025). "Diabetes increased renal cortical expression of IL-6 and phosphorylated STAT3, which was inhibited by NaHS." (PMID 39782685, 2025). "Research has shown that STAT3 can regulate diabetes by controlling hepatic glucose metabolism, including gluconeogenesis and glycolysis, as well as insulin sensitivity." (PMID 40733369, 2025). "NaB ameliorated diabetes-related sarcopenia through the ILC2s/IL-13/STAT3 pathway, and dietary NaB supplementation promoted the expressions of myosin heavy chain I (MyHCI) and MyHCIIα to promote oxidative fiber growth in skeletal muscle." (PMID 40005024, 2025). "In diabetic db/db mice, administration of DAPA remarkably ameliorated diabetes-induced STAT3 activation, YY1 nuclear translocation, CF proliferation and activation, and reduced cardiac fibrosis and dysfunction." (PMID 41170186, 2025). "Similar to what has been observed in patients with diabetes, high glucose levels can impair the IL-10 signaling protein—signal transducer and activator of transcription 3 (STAT3)—and lead to IL-10 hyporesponsiveness." (PMID 39062154, 2024).
diabetes (continued). "It was thus found that diabetes-induced CD8+ T-cell responses are restricted in the presence of normal STAT3 activity and drive diabetic pathogenesis." (PMID 38800484, 2024). "Our results suggest that diabetes caused notable increases in the phosphorylation of JAK2 and STAT3 and the levels of TGF-β1." (PMID 36597092, 2023). "In Wayne’s analysis, we selected target genes related to peripheral nerves, autophagy and diabetes, including Stat3." (PMID 38001489, 2023). "It should be noted that compared to STAT3 GOF, there was incomplete penetrance but also differences in manifestation (SLE in SOCS1 haploinsufficiency vs. enteropathy and diabetes in STAT3 GOF)." (PMID 37140667, 2023). "Treatment with irisin was found to block the p38, STAT3 and Nf-κB proteins, reducing diabetes-induced neuroinflammation in the brain of mice Another study revealed that 100 nm/L irisin promoted cell proliferation via the STAT3 pathway." (PMID 36843614, 2023). "TF Rfx1is playing downstream role on signal transducer and activator of transcription 3 (STAT3) pathway while the expression of Rfx1 is regulated by interleukin-6 (IL-6)-STAT3 signaling pathway, and STAT3 plays an important role in diabetes pathogenesis." (PMID 36037214, 2022). "MAPK1 is known to suppress STAT3 activation enzymatically and is proposed as a valuable candidate for diabetes therapy." (PMID 36159557, 2022). "In the STZ-induced diabetes animal model and the in vitro high glucose (HG)-stimulated renal tubular epithelial cells, the activation of STAT3 was found." (PMID 35956419, 2022). "This indicated that exercise inhibited the JAK2/STAT3 pathway, which is likely one of the mechanisms by which aerobic exercise improves the symptoms of diabetes." (PMID 35578689, 2022). "Taken together, our data indicated that long-term aerobic exercise improves type 2 diabetes mellitus-related cognitive impairment by inhibiting JAK2/STAT3 and enhancing AMPK/SIRT1 pathways in mice." (PMID 35578689, 2022). "Our findings corroborate accumulating evidence illuminating the role of EZH2 and STAT3 in diabetes mellitus-related or neurological diseases." (PMID 34857740, 2021). "The MAPK1/STAT3 pathway has been proposed as a novel diabetes target for its critical role in glucose homeostasis." (PMID 34362956, 2021). "Previous studies have found that STAT3 in the nerve center of knockout mice can lead to obesity, diabetes, and energy imbalance." (PMID 33833859, 2021). "A Ras family GTPase, Ras-related associated with diabetes (RRAD), contributes to activation of STAT3, which is essential for survival and growth of many cancer types." (PMID 33980886, 2021). "The JAK2/STAT3/SOCS axis plays a crucial role in the development of diabetes, where overexpression and phosphorylation of JAK2 were observed." (PMID 34067609, 2021). "In order to further explore the function of PIAS1 in diabetic neuropathy, adenovirus stably overexpressing PIAS1, EZH2, and STAT3 was infected into db/db mice with spontaneous type 2 diabetes mellitus." (PMID 34857740, 2021). "For example, empagliflozin reduces IS by increasing STAT3 phosphorylation at early reperfusion in in vivo hearts of mouse fed weed western diet to induce diabetes." (PMID 34642818, 2021). "Our results suggest that the metformin/MBNL1/miR-130a-3p/STAT3 pathway is involved in regulating the senescence and pathological changes in renal tubular epithelial cells in diabetes." (PMID 32104542, 2020). "Diabetes-mediated inflammation and hyperglycemia activate RORγt, wherein hyperglycemia-driven IL-6 and glucose sensitive stimulatory factors co-activate a STAT3 signaling cascade that activates RORγt." (PMID 32429598, 2020). "In this study, we investigated the role of the signal transducer and activator of transcription 3 (STAT3) pathway in diabetes-induced immune cell activation and its contribution to retinal microvascular degeneration." (PMID 31286987, 2019).
diabetes (continued). "Antioxidant NAC preserves RPC-induced cardioprotection by improving Cav-3-dependent Akt and STAT3 activation and by facilitating the cross talk between PI3K/Akt and JAK2/STAT3 signaling pathways in diabetes." (PMID 31583053, 2019). "In the same context, streptozotocin-induced diabetes resulted in cardiac STAT3 activation in C57BL/6 mice." (PMID 31709266, 2019). "This study uncovered the novel role of the IL-6/STAT3 pathway in diabetes-induced circulating immune cell activation, and the development of diabetic retinal vasculopathy." (PMID 31286987, 2019). "Based on these results, we conclude that EULE improved diabetes-associated ED by increasing Akt and eNOS bioactivity and suppressing JNK and STAT3 activation to restore endothelial function." (PMID 31467570, 2019). "Our study suggests that STAT3 activation in leukocytes also contributes to diabetes-induced vascular damage." (PMID 31286987, 2019). "The additional investigation of STAT3 activation suggests that propofol restores hyperglycemia/diabetes-induced reduction in STAT3 phosphorylation." (PMID 31527528, 2019). "Our results suggest that STAT3-driven immune cell activation plays an important role in early diabetes-induced microvascular degeneration." (PMID 31286987, 2019). "In summary, the majority of articles revealed that diabetes attenuates ischaemic or pharmacological conditioning-induced cardiac STAT3 activation after ischaemia/reperfusion." (PMID 30424579, 2018). "After five weeks of diabetes induction, they found that myocardial STAT3 activation (at the Ser727 site) was lower in the diabetic group." (PMID 30424579, 2018). "Several publications demonstrated a significant decrease in cardiac STAT3 phosphorylation and/or activation in various experimental models of diabetes." (PMID 30424579, 2018). "In summary, post-ischaemic STAT3 phosphorylation and/or activation are significantly decreased due to diabetes in all studies irrespective of the applied models, which may contribute to increased susceptibility to myocardial ischaemia/reperfusion injury in diabetes." (PMID 30424579, 2018). "In summary, the findings regarding the effect of diabetes on cardiac STAT3 phosphorylation, expression and activation are inconsistent." (PMID 30424579, 2018). "In contrast to discrepancies regarding the effect of diabetes on infarct size, post-ischaemic phosphorylation/activation of cardiac STAT3 was clearly downregulated in experimental models of diabetes in all investigations." (PMID 30424579, 2018). "In some studies, the phosphorylation/activation of STAT3 was also increased in response to various cardioprotective agents in diabetes models." (PMID 30424579, 2018). "Recently some potential cardioprotective agents have been suggested to attenuate STAT3 dysregulation in diabetes." (PMID 30424579, 2018). "For instance, the activation of cardiac STAT3 was increased four weeks after the induction of diabetes with STZ injection in C57BL/6 mice." (PMID 30424579, 2018). "It is highly efficacious in ameliorating several chronic diseases such as asthma, diabetes, cancers of breast, cervical, stomach, etc. via the inhibition of STAT3, NF-κB, PGE2, IL-6, TNF-α, etc.." (PMID 29370858, 2018). "In another study using an STZ-induced rat diabetes model, telmisartan attenuated STAT3 expression, which was increased by diabetes." (PMID 30424579, 2018). "We screened all participants for the seven genes known to cause monogenic autoimmunity that can include diabetes (AIRE, IL2RA, FOXP3, LRBA, STAT1, STAT3, STAT5B)." (PMID 29417186, 2018). "This reduction of post-ischaemic STAT3 phosphorylation and/or activation due to diabetes was confirmed by several studies of another research group in the ischaemic tissue as well as in whole heart or ventricular tissue samples." (PMID 30424579, 2018). "The impaired activation or phosphorylation of STAT3 due to STZ-induced diabetes was shown to be restored by N-acetylcysteine." (PMID 30424579, 2018).
diabetes (continued). "Later the same research group confirmed these results in STZ-induced type I diabetes models and demonstrated that phosphorylation and activation of STAT3 at Tyr705 was also decreased in diabetes." (PMID 30424579, 2018). "Here, we provided new evidence that SOCS3 and STAT3 gene expression were also elevated in the late period of diabetes, as the present study was conducted for 32 weeks." (PMID 29318137, 2017). "This study investigated the role of the JAK2/STAT3/SOCS pathway in type 2 diabetes mellitus (T2DM) and macrovascular complications (DV) (T2DM+DV) conditions." (PMID 29228585, 2017). "Targeted deletion of STAT3 in the brain in a rodent model leads to the development of obesity and diabetes mimicking the phenotype of ob/ob or db/db mice; however, these data have not yet been confirmed in human studies." (PMID 27834824, 2016). "N-Acetylcysteine restored Sevo-postC cardioprotection in diabetes possibly through enhancing cardiac p-STAT3 and adiponectin and reducing Fox1 and CD36." (PMID 26783539, 2016). "In diabetes, the activation of myocardial STAT3 was markedly decreased, whereas the expression of FoxO1 was upregulated." (PMID 26783539, 2016). "Several studies have reported that cardiac Stat3 and phospho-Stat3 expression were reduced in diabetes, which can lead to cardiac dysfunction." (PMID 27496100, 2016). "Diabetes can cause impairments to both phosphatidylinositol 3-kinase- (PI3K-) Akt and Janus kinase (Jak-) STAT3, which are the two classic signaling pathways of myocardial protection mechanisms and thus obstruct the postconditioning of myocardium." (PMID 26783539, 2016). "Diabetes showed reduction of cardiac STAT3 activation (p-STAT3) and adiponectin with concomitantly increase of FoxO1 and CD36, which associated with reduced sevo-postC cardioprotection." (PMID 26783539, 2016). "Those include SOCS3 which in cell culture is β-cell protective, however, by curbing protective STAT3 signaling in vivo, seemingly is pathogenic as detected using a β-cell-specific knockdown during STZ-induced diabetes." (PMID 26793108, 2015). "This hyperglycemia-induced increase of IRI in diabetes can be prevented by treatment with antioxidants, N-Acetylcysteine and allopurinol, by activating both the Akt and STAT3 involved signaling pathways." (PMID 24041262, 2013). "It is possible that the sensitized STAT3 phosphorylation accompanied by reduced SOCS3 activation in DM myocytes is a dysregulation compensating for other diabetes related alterations in cell signaling in skeletal muscle." (PMID 22761857, 2012). "Recent findings have suggested that diabetes increases the level of STAT3 activation and thereby contributes to the pathophysiology of vascular injury." (PMID 23094067, 2012). "The angiotensin converting enzyme inhibitor enalapril has been demonstrated to prevent the diabetes-induced up-regulation of Stat3 protein." (PMID 21249158, 2011). "In summary, this study demonstrated that, in the early stages of STZ-induced diabetes, rats displayed APN deficiency and increased inflammatory cytokines together with reduced cardiac AdipoR2 expression and impaired Akt-eNOS and STAT3-eNOS activation." (PMID 21912612, 2011). "Stat3 activation by diabetes and subsequent blood retinal barrier damage can be prevented by simvastatin treatment." (PMID 21249158, 2011). "Moreover, miR‐125a‐5p demonstrates significant ties to metabolic derangements, notably ameliorating glycolipid metabolic abnormalities in type 2 diabetes mellitus through STAT3 modulation." (PMID 41523988, 2026). "Across diabetes, myocardial infarction, heart failure, and neuroinflammatory states, shared pathways (e.g., IL-6/STAT3, TGF-β/SMAD, PI3K/AKT, MAPK/ERK, oxidative stress) suppress neuronal excitability, promote neuron-glia-fibroblast coupling, and culminate in neurofibrotic remodeling." (PMID 41684000, 2026).
diabetes (continued). "Additionally, myricetin and rutin have been shown to modulate various diseases, including diabetes, atherosclerosis, and inflammation-related disorders, through the STAT3, AKT1, and PIK3R1 signaling pathways." (PMID 40356949, 2025). "The results of molecular docking indicated that the active ingredients of Jerusalem artista might be combined with PPARG and STAT3 to treat diabetes, and the results of molecular docking further proved the accuracy of the network pharmacological screening." (PMID 41189218, 2025). "In a majority of patients with STAT3 GOF variants, profound growth retardation is exhibited and this may be related to gastrointestinal disease, diabetes, hypothyroidism, recurrent infections, or immunosuppressive treatment." (PMID 38404237, 2024). "The importance of STAT3 function in immune regulation is demonstrated by the clinical manifestations in STAT3 gain-of-function (GOF) syndrome which often include early-onset autoimmunity including endocrinopathy with type 1 diabetes mellitus and thyroid disease." (PMID 39359478, 2024). "It has been shown that downregulating the expression of MAPK1 could enzymatically inhibit the activation of proteins related to IR, such as STAT3, and had been proposed as a valuable candidate target for diabetes treatment." (PMID 39534794, 2024). "The deregulated JAK/STAT3 pathway is a common factor in endometrial cancer and diabetes." (PMID 39188680, 2024). "Notably, a reported case, attributed to the STAT3 GOF variant p.Pro330Ser, manifested neonatal diabetes accompanied by detectable islet autoantibodies, autoimmune hypothyroidism, and enteropathy." (PMID 38404237, 2024). "Taken together, these key findings suggest that miR-221-3p may directly inhibit the expression of DYRK1A to regulate the inflammatory response of epithelial tissues mediated by the STAT3 signaling pathway and thus promote skin wound healing in diabetes." (PMID 38461326, 2024). "A further 10 patients with STAT3 GOF phenotype have been reported to have early‐onset diabetes." (PMID 38404237, 2024). "In addition to increases in reactive oxygen species (ROS) and oxidative stress, increases in inflammation, reduction in cardiac Akt and STAT3 all occur in the myocardium of diabetes." (PMID 38283744, 2023). "Recent studies have demonstrated elevated levels of phosphorylated signal transducer and activator of transcription 3 (pSTAT3), a key regulatory molecule in cell signaling, in circulating myeloid (monocyte/macrophage) cells from patients with diabetes and in STZ-induced diabetic mice.." (PMID 38124748, 2023). "Modulating the Talin-1/Smurf1/Stat3 axis in pancreatic islet β-cells could serve as a promising therapeutic approach for patients with diabetes." (PMID 37903776, 2023). "Moreover, two master transcription factors, STAT3 and NF-κB were activated in HG conditions, both of which are well documented in the development of diabetes and its complications." (PMID 36463298, 2022). "STAT3 in our study was recognized as a key protein interaction based on PPI network analysis with a high score GDA that introduced this gene as one of the critical therapeutic targets for diabetes." (PMID 35956419, 2022). "Moreover, genetic ablation of STAT3 in a mouse model results in partial amelioration of muscle wasting under the induction of diabetes, chronic kidney disease, and cachexia." (PMID 36127129, 2022). "Polymorphisms of BTNLs and sometimes their deficits have been associated with chronic kidney disease, hypertension and diabetes; Nlrc5, a pattern recognition receptor in the MHC I class, regulates NF-κB, type 1 interferon activities and JAK/STAT3 signaling in immune response pathways." (PMID 34204247, 2021). "Activated STAT3 can be implicated in the activity of downstream mediators such as p27kip1, P16INK4A, and p21kip1 proteins, which regulate cell growth, differentiation, and angiogenesis and are involved in the pathogenesis of diabetes." (PMID 34159207, 2021).